CCDC47 (coiled-coil domain containing 47)
Description:
Component of the multi-pass translocon (MPT) complex that mediates insertion of multi-pass membrane proteins into the lipid bilayer of membranes. The MPT complex takes over after the SEC61 complex: following membrane insertion of the first few transmembrane segments of proteins by the SEC61 complex, the MPT complex occludes the lateral gate of the SEC61 complex to promote insertion of subsequent transmembrane regions. Within the MPT complex, the PAT subcomplex sequesters any highly polar regions in the transmembrane domains away from the non-polar membrane environment until they can be buried in the interior of the fully assembled protein (By similarity). Within the PAT subcomplex, CCDC47 occludes the lateral gate of the SEC61 complex (By similarity). Involved in the regulation of calcium ion homeostasis in the ER. Required for proper protein degradation via the ERAD (ER-associated degradation) pathway. Has an essential role in the maintenance of ER organization during embryogenesis (By similarity).
Synonyms: GK001; MSTP041; THNS
Tractability: Antibody: UniProt predicts a signal peptide or a membrane-spanning region. PROTAC: ubiquitination databases record sites on it; its protein half-life has been measured.
Gene: Protein-coding gene on chromosome 17 (63,745,255 to 63,776,351, reverse strand). Ensembl gene ENSG00000108588.
Subcellular location: Endoplasmic reticulum membrane; Rough endoplasmic reticulum membrane
Subcellular location (Human Protein Atlas): Endoplasmic reticulum
Gene Ontology:
Molecular function: protein binding; protein folding chaperone; ribosome binding; RNA binding; calcium ion binding
Biological process: endoplasmic reticulum calcium ion homeostasis; ERAD pathway; multi-pass transmembrane protein insertion into ER membrane; osteoblast differentiation; protein insertion into ER membrane; protein folding
Cellular component: endoplasmic reticulum; endoplasmic reticulum membrane; membrane; multi-pass translocon complex; protein folding chaperone complex; rough endoplasmic reticulum membrane; rough endoplasmic reticulum
Genetic constraint (gnomAD): Loss-of-function variants: 36 observed, 51.79 expected, observed/expected ratio (o/e) 0.7, 90% interval 0.53 to 0.92. The upper end of that interval is the gene's LOEUF score, 0.92, which puts it in group 3 of 6, group 1 being the genes least tolerant of losing a copy. Missense variants: 481 observed, 558.84 expected, observed/expected ratio (o/e) 0.86, 90% interval 0.8 to 0.93. Synonymous variants: 183 observed, 187.95 expected, observed/expected ratio (o/e) 0.97, 90% interval 0.86 to 1.1.
Homologues: Orthologues: chimpanzee CCDC47 (100% identical), macaque CCDC47 (99% identical), dog CCDC47 (99% identical), rabbit CCDC47 (99% identical), pig CCDC47 (98% identical), mouse Ccdc47 (98% identical), rat Ccdc47 (98% identical), guinea pig CCDC47 (98% identical), tropical clawed frog ccdc47 (81% identical), zebrafish ccdc47 (77% identical), Drosophila melanogaster CG17593 (43% identical), Caenorhabditis elegans ccdc-47 (34% identical).
Diseases named in the same sentence as CCDC47 in open-access papers:
CCDC47 is named in the same sentence as 11 diseases in open-access papers, as found by Europe PMC text mining. Sharing a sentence is not in itself a finding about the gene and the disease. The quoted sentences say what the papers report.
trichohepatoneurodevelopmental syndrome (2 papers, 2022 to 2025). "CCDC47 has been previously linked to trichohepatoneurodevelopmental syndrome (MIM 618268) which presents an overlapping phenotype to UDP4 (CCDC47)." (PMID 40400026, 2025).
adrenocortical carcinoma (1 paper, 2022). "Only one such case was identified in the cohort of adrenocortical carcinoma profiled by TCGA (TCGA-OR-A5JS) and this case harbored a CCDC47-TERT fusion." (PMID 34549366, 2022).
atrial fibrillation (1 paper, 2018). A disorder characterized by an electrocardiographic finding of a supraventricular arrhythmia characterized by the replacement of consistent P waves by rapid oscillations or fibrillatory waves that vary in size, shape and timing and are accompanied by an irregular ventricular response. "Another possibility is that the early increase in CCDC47 protein levels in the atrium may play a role in atrial fibrillation." (PMID 30140426, 2018).
cardiomyopathy (1 paper, 2018). A disease of the heart muscle or myocardium proper. "Thus, we chose to further investigate CCDC47 and its association with cardiomyopathy." (PMID 30140426, 2018). "Together, these studies demonstrate that dysregulation of CCDC47 may play a role in diet-induced cardiomyopathy." (PMID 30140426, 2018). "Moreover, this is the first report to identify altered expression of CCDC47 in a DIO model of cardiomyopathy." (PMID 30140426, 2018). "CCDC47 (calumin) was identified as a unique protein that has not previously been associated with cardiomyopathy." (PMID 30140426, 2018). "Thus, it is possible that in a chronic or stable cellular model of cardiomyopathy calcium signaling may in turn affect CCDC47 expression." (PMID 30140426, 2018). "Very little is known about CCDC47 and to the best of our knowledge there are no studies linking CCDC47 to cardiomyopathy." (PMID 30140426, 2018).
glaucoma (1 paper, 2020). Increased pressure in the eyeball due to obstruction of the outflow of aqueous humor. "In humans, TMCO1 has been linked to glaucoma, and loss of either TMCO1 or CCDC47 causes rare autosomal recessive developmental disorders." (PMID 32820719, 2020).
hypertrophic cardiomyopathy (1 paper, 2018). A condition in which the myocardium is hypertrophied without an obvious cause. "Together, our in vitro and in vivo studies demonstrate that CCDC47 is a unique calcium regulating protein that is associated with early onset hypertrophic cardiomyopathy." (PMID 30140426, 2018).
CCDC47 also shares sentences with these, for which no sentence is quoted: breast carcinoma (1 paper); diabetic cardiomyopathy (1); Obesity (1); oral cancer (1); tumor (1).